MIR766 (microRNA 766)
Synonyms: hsa-mir-766; MIRN766; mir-766
Gene: MicroRNA gene on chromosome X (119,646,738 to 119,646,848, reverse strand). Ensembl gene ENSG00000211578.
Homologues: Orthologues: chimpanzee ptr-mir-766 (100% identical).